RPL30-AS1 (RPL30 antisense RNA 1)
Synonyms: KB-1208A12.3; AP003352.1
Gene: Long non-coding RNA gene on chromosome 8 (98,041,726 to 98,044,121, forward strand). Ensembl gene ENSG00000245970.
Gene Ontology:
Biological process: RNA processing
Cellular component: nucleolus
Diseases named in the same sentence as RPL30-AS1 in open-access papers:
RPL30-AS1 is named in the same sentence as 1 disease in open-access papers, as found by Europe PMC text mining. Sharing a sentence is not in itself a finding about the gene and the disease.
RPL30-AS1 shares sentences with these, for which no sentence is quoted: osteosarcoma (1 paper).